HIF1A (hypoxia inducible factor 1 subunit alpha)
Diseases named in the same sentence as HIF1A in open-access papers (continued):
Sharing a sentence is not in itself a finding about the gene and the disease.
tumor (continued). "Several tumor progression-associated genes, such as Hif1a and Parva, were significantly upregulated in the CAF-Sfrp1 group." (PMID 40225580, 2025). "As the tumor progresses to late stages, chronic hypoxia causes a gradual transition from HIF1A to EPAS1/HIF-2α dominance." (PMID 40851276, 2025). "HIF1A is also implicated in tumor immunity, angiogenesis, metabolic processes, and cell cycle regulation." (PMID 40948653, 2025). "We determine diverse metabolic profiles and patients’ survival, as well as specific markers in tumour metabolism associated with the differential WWOX/HIF1A ratio." (PMID 41007296, 2025). "HIF-1α is primarily associated with the early stages of tumor development and is more widely studied for its role in initiating adaptive responses to hypoxia." (PMID 40901111, 2025). "Hypoxia can promote the infiltration and dissemination of neoplastic cells by activating a series of signaling pathways associated with tumor aggressiveness, such as the HIF-1α signaling pathway." (PMID 40129974, 2025). "HIF-1α governs the migration of macrophages to hypoxic areas inside the tumor and controls the expression of several genes implicated in tumor angiogenesis." (PMID 40290126, 2025). "It is proposed that mutual activation between HIF-1α and NF-ĸB/iNOS contributes to ongoing DNA damage, potentially leading to increased tumor invasiveness through mutations and, ultimately, a worse prognosis." (PMID 40244228, 2025). "In contrast, a high WWOX/HIF1A ratio is associated with pathways indicative of poor prognosis, including genomic instability, uncontrolled proliferation, and tumour progression." (PMID 41007296, 2025). "HIF-1α has also been implicated in the response of the tumor microenvironment (TME) to radiotherapy." (PMID 40867316, 2025). "Quantification of EPO protein in ccRCC showed that the loss of HIF1A protein was associated with very low EPO expression, while the HIF1A presence in the tumor indicated a strong upregulation of EPO compared to HIF1A-negative tumors (p < 0.001)." (PMID 40332447, 2025). "Dividing the tumors into those that express the wild-type VHL gene and those with the mutated VHL gene, the quantification of HIF1A revealed decreased expression in both tumor types compared to the surrounding healthy tissue." (PMID 40332447, 2025). "Recent studies have extensively investigated the mechanisms underlying angiogenesis in tumor cells, revealing the involvement of lncRNAs and HIF-1α in various stages of the angiogenic response." (PMID 40861273, 2025). "The tumor macrophages displayed prominent upregulation of HIF1A, a gene that when detected on TAMs has been implicated in cancer progression, T cell suppression, and metastasis." (PMID 40848148, 2025). "Activation of HIF-1α promotes the recruitment of inhibitory cells, including myeloid-derived suppressor cells (MDSCs), Tregs, and M2-type tumor-associated macrophages." (PMID 40655149, 2025). "Critically, WWOX loss triggers HIF1α stabilization, inducing metabolic rewiring that fuels tumour growth and aggressiveness." (PMID 41007296, 2025). "Supporting this possibility, the LC-iCAP readout includes robust activation of the HIF1A-mediated hypoxia response pathway, a hallmark of tumor biology." (PMID 40831733, 2025). "In contrast, preexisting tumor hypoxia and PDT-induced hypoxia activate hypoxia-inducible factor 1α (HIF-1α), which is strongly associated with poor prognosis and tumor progression." (PMID 40051791, 2025). "This process is often associated with hypoxia in tumor cells, and HIF-1α induces the production of fatty acid synthase in cancer cells, thus shifting the metabolism from glucose metabolism and acetyl coenzyme A to lipid metabolism." (PMID 40696413, 2025).
tumor (continued). "HIF-1α upregulation causes a cascading effect, where tumour cells and surrounding stromal cells start secreting pro-angiogenic molecules that stimulate the overexpression of pro-angiogenic factors (VEGF, FGF, PDGF-B, and angiopoietins)." (PMID 40427172, 2025). "Among these parameters, HIF-1α expression was significantly associated with tumor stage (p = 0.036) and DOI (p = 0.027)." (PMID 40546546, 2025). "This causes the tumor cells to activate HIF1α in tumor cells along with SDF1 and VEGF, which attract endothelial progenitor cells." (PMID 40341988, 2025). "The genetic defect leads to the accumulation of HIF-1a protein, activating key carcinogenic pathways, and activated cytokines cause abnormal proliferation of tumor cells and oncogenesis." (PMID 41640149, 2025). "In TNBC the LKB1 deficiency promotes tumor growth and metastasis by enhancing glycolysis and activating the mTOR- HIF-1α axis, which supports TNBC cells survival and proliferation under metabolic stress." (PMID 41436543, 2025). "The increased reliance of tumour cells on glutamine metabolism is linked to Hypoxia-Inducible Factor 1-alpha (HIF-1α) activity." (PMID 41515893, 2025). "We observed a significant relationship between PD-L1 and HIF-1α expression, as well as between KRAS G12C mutations and HIF-1α expression in the tumor microenvironment." (PMID 39996842, 2025). "HIF-1α up-regulation is significantly associated with lymph node metastasis and distant metastasis, and is involved in tumor growth, metabolism, angiogenesis, and metastasis by regulating gene expression." (PMID 40530008, 2025). "Further analysis of human cancers identified a subset of HIF-1α target genes involved in extracellular matrix remodeling, a key hallmark of aggressive tumor behavior." (PMID 39470609, 2025). "A low WWOX/HIF1A ratio in Luminal A tumours correlates with pathways linked to favourable prognosis, including modulation of metabolic pathways, reduced glycolysis, and regulation of cell survival and proliferation." (PMID 41007296, 2025). "Hif-1α-activated Notch signaling can promote CSCs-associated tumor metastasis in lung, ovarian, and breast cancer." (PMID 41281744, 2025). "In the TME, HIF-1α recruits and increases the function of suppressive cells, including tumor-associated macrophages and MDSCs." (PMID 40072059, 2025). "Apigenin treatment also resulted in decreased expression levels of key proteins associated with glycolysis and tumor progression, including HIF-1α, GLUT-1/3, NF-κB p65, and PKM2." (PMID 41009025, 2025). "Elevated expression of HIF1A is often associated with the formation of tumor blood vessels, and the increase in neovascularization can contribute to the distal metastasis of tumor cells." (PMID 40085529, 2025). "High levels of HIF-1α have been linked to increased tumor size, higher grade, and a greater likelihood of metastasis." (PMID 40901111, 2025). "Tumor with higher expression of HIF-1α can be associated with serious local hypoxia, where the tumor is mainly anaerobic metabolism, leading to increased production of local lactic acid and reduced pH value." (PMID 40444079, 2025). "The increased angiogenesis in PAK4KO tumours was associated with a reduction in hypoxia, as shown by a decreased HIF-1α expression." (PMID 41294859, 2025). "In our study, HIF-1α overexpression was associated with higher tumor stage and increased DOI, indicating a more aggressive disease at presentation." (PMID 40546546, 2025). "Studies have shown that tumour-associated myeloid cells (TAMCs) in hypoxic regions of GBM synthesise creatine via HIF1α-dependent metabolic pathways." (PMID 40630800, 2025). "GLUT1 and HIF1a were elevated in the margin, suggesting stemness, metabolic adaptation, and hypoxic conditions linked to aggressive tumor biology and potential invasiveness." (PMID 40431665, 2025).
tumor (continued). "A central feature of this process is the HIF-1α–mediated upregulation of immune checkpoint ligands, particularly programmed death-ligand 1 (PD-L1), on tumor cells and associated stromal cells." (PMID 40963621, 2025). "In GC, HIF‐1α expression demonstrates upregulation in serum and tumor tissues, associating with enhanced proliferation, migration, and invasion via PI3K/AKT‐triggered VEGF production." (PMID 40740483, 2025). "The upregulation of glycolytic mediators, such as GLUT-1, in PanNETs has repeatedly been correlated with malignant potential and is often linked to increased HIF-1α expression in hypoxic tumor areas." (PMID 41458541, 2025). "Dysregulation of HIF‐1α stability, particularly its stabilization under normoxic conditions, is a hallmark of cancer and contributes to tumor progression, angiogenesis, and metastasis." (PMID 40227962, 2025). "Abnormal proliferation and malignancy of tumor tissues during GC development increase HIF-1α, raising the risk of early GC occurrence." (PMID 40458722, 2025). "The co-expression of PD-L1 and HIF-1α is associated with poor prognosis, as these molecules collectively promote immune evasion and tumor progression." (PMID 39996842, 2025). "Specifically, HDAC8 increases the stability of HIF-1α via histone deacetylation, thereby increasing its ability to activate target genes associated with tumor progression by boosting glycolysis and metastasis formation." (PMID 40573249, 2025). "Exposure to VEGF-targeting medication results in tumor hypoxia, causing tumor cells to release HIF1α that stimulates the epithelial cells to acquire mesenchymal characteristics, also known as epithelial-mesenchymal Transition (EMT)." (PMID 40341988, 2025). "In the field of oncology, numerous clinical studies have demonstrated that the overexpression of HIF-1α in tumors is significantly associated with tumor size, metastasis, and poor prognosis." (PMID 40887582, 2025). "In contrast, HIF‐1α is often stable under hypoxic conditions and is associated with poor tumour prognosis." (PMID 40954549, 2025). "In cancer-associated fibroblasts, the increased expression of HIF-1α can amplify vascular functionality and bolster blood perfusion, ultimately contributing to elevated tumor progression." (PMID 40821116, 2025). "Conversely, a lower WWOX/HIF1A ratio is associated with aggressive tumour behaviour characterized by enhanced glycolysis, angiogenesis, immune evasion, and dysregulated survival signalling pathways." (PMID 41007296, 2025). "Accordingly, the build‐up of R‐2‐HG caused by IDH1/2 mutations decreases HIF‐1α levels and encourages tumor development, which includes astrocyte cancer." (PMID 40567251, 2025). "Tumour hypoxia is a hallmark of solid tumours and plays a pivotal role in cancer resistance by promoting angiogenesis via the HIF-1α pathway, driving epithelial−mesenchymal transition, invasion, metastasis and stem-like traits, as well as enhancing glycolysis." (PMID 40867257, 2025). "A statistically significant association was observed between HIF-1α overexpression and both higher tumor stage and greater DOI, supporting its link to more aggressive disease behavior." (PMID 40546546, 2025). "For example, SFV infection significantly reduced 4T1-upregulated Pdgfa levels, while inducing Vegfa and Hif1a expression, markers commonly associated with hypoxia and tumour progression." (PMID 40547518, 2025). "In particular, only 1 key gene (HIF1A) was found to be associated with tumor purity and tumor-infiltrating immune cells in all 4 types of gastrointestinal cancers." (PMID 39928794, 2025).
tumor (continued). "HIF-1α overexpression was observed in 18 Khasi patients, 13 of whom had higher tumor grade and DOI >5 mm, supporting the association between HIF-1α overexpression and advanced disease at diagnosis." (PMID 40546546, 2025). "When C6 glioma cells were implanted in Wistar rats, HSP prevented tumour growth by activating caspase-3 and -9, raising the Bax/Bcl-2 ratio, which caused apoptosis, and downregulating the HIF-1α, VEGF, and VEGFR2 signalling pathways." (PMID 40427522, 2025). "In this regard, the potential risk of exacerbating tumor growth through the activation of HIF-1α signaling in the management of cancer-related anemia necessitates thorough evaluation." (PMID 41311849, 2025). "Gold nanoparticles linked to HIF-1α inhibitors improve tumor-specific inhibition, reducing angiogenesis and tumor hypoxia." (PMID 40136686, 2025). "KRAS mutation status was evaluated alongside PD-L1 expression in tumor cells and HIF-1α expression in both tumor cells and the tumor microenvironment." (PMID 39996842, 2025). "Many biological changes associated with tumor hypoxia are mediated by the induction of hypoxia-inducible factors (HIFs), including HIF-1α." (PMID 39863855, 2025). "Uncontrolled HIF-1α activation can cause vascular damage, worsening diseases like retinopathy, or activate tumor vasculature." (PMID 41150799, 2025). "Clinical studies suggest that bortezomib’s ability to inhibit tumor angiogenesis and hypoxic adaptation is associated with its repression of HIF-1α transcriptional activity." (PMID 39757165, 2025). "SFV infection significantly reduced 4T1-upregulated Pdgfa levels, while increasing Vegfa and Hif1a expression, markers commonly associated with hypoxia and tumour progression." (PMID 40547518, 2025). "hiTDExs carry specific biomarkers including miRNAs (e.g., miR-21, miR-1246), proteins (e.g., PKM2, HIF1A), and circular RNAs (e.g., circPLEKHM1) that are directly linked to tumor hypoxia." (PMID 39928285, 2025). "Here, authors report that ASH1L cooperates with HIF-1α to induce a pro-metastatic transcriptome in prostate cancer cells, and promotes conversion of monocytes to lipid-associated tumor-associated macrophages in the bone metastatic niche." (PMID 40394007, 2025). "As already discussed, hypoxia is a characteristic trait of tumor microenvironment and is associated with the overexpression of HIF-1α, a protein commonly correlated with tumor metastasis." (PMID 40468341, 2025). "Current research focuses on mitochondrial DNA mutations, the regulation of hypoxia-inducible factor (HIF-1α), and alterations in key enzymes such as hexokinase-II (HK-II), and their effects on tumor cells’ response to chemotherapy." (PMID 39611141, 2024). "Evidence suggests that HIF-1α expression is linked to tumor promotion in human OSCC and correlates with the growth of human OSCC cells." (PMID 38474118, 2024). "NAMPT plays a pivotal role in Tumor‐associated macrophages (TAMs) reprogramming by regulating the HIF‐1α/STAT3 and a reduction in STING activation." (PMID 38308188, 2024). "HIF-1α affects glucose metabolism in tumor cells by inducing the genes encoding glucose transporter 1 (GLUT1) and glycolytic enzymes." (PMID 38236337, 2024). "This coupled with increased expression of VEGF-A, stimulated by hypoxic inducible factor (HIF)-1α causes pro-angiogenic effects in EC, related to tumor growth and angiogenesis." (PMID 39511039, 2024). "Past research has linked SAA proteins to advanced tumor stages, lymphovascular invasion, lymph node metastasis, and increased HIF1α expression." (PMID 39336082, 2024). "Hypoxia stimulates the hypoxia‐inducible factor‐1α (HIF‐1α) that transactivates genes associated with angiogenesis, tumour growth, metastasis, metabolic reprogramming, immune evasion and treatment resistance." (PMID 39660488, 2024).
tumor (continued). "The induction of Ogr1 in tumor tissue is in good agreement with the known interaction between tumor hypoxia and acidosis, and several putative DNA binding sites for HIF-1α within the proximal regions of the Ogr1 promoter variants have been identified." (PMID 38514581, 2024). "This process can be stopped by a number of stimuli in the tumour microenvironment, which causes the production of the HIF‐1α protein to increase the rate of aerobic glycolysis in tumour cells." (PMID 38229475, 2024). "A meta-analysis of nine studies (1103 subjects) found that half of GC patients have HIF-1α-expressing tumours associated with lower five-year survival, deeper invasion, higher lymphatic/vascular invasion risk, and advanced TNM stage." (PMID 39816318, 2024). "Lactic acid released by glycolytic tumor cells can up-regulate hypoxia-inducible factor-1 alpha (HIF-1α)-stabilizing long noncoding RNA (HISLA) in tumor-associated macrophages (TAMs), forming a feedforward loop between TAM and tumor cells." (PMID 39588377, 2024). "This suggests a link between the ROS activation of HIF-1α and abnormal expression of miRNAs associated with tumour progression." (PMID 39594467, 2024). "The KC26-Lipo system works by inhibiting lactate metabolism in breast cancer, repolarizing tumor-associated macrophages (TAMs), and suppressing tumor angiogenesis through the HIF-1α/VEGF pathway." (PMID 39654883, 2024). "Hypoxia is a common characteristic of both primary and metastatic BC, with HIF-1α expression in tumor tissues associated with poor prognosis and drug resistance." (PMID 38799423, 2024). "HIF-1α acts a transcription factor to regulate the transcription of multiple metabolic enzymes, thereby causing tumor metabolic reprogramming." (PMID 39343971, 2024). "OSA-related IH activated HIF-1α and its associated signaling pathways, enhanced the expression of PD-L1 in tumor cells, and increased the activity of TAMs while decreasing cytotoxic T cell activity." (PMID 38605948, 2024). "Instead, we point out a reciprocal loop of C/EBPδ and HIF-1α, the main mediator of the response to hypoxia, which likely contributes to the loss of C/EBPδ’s tumor suppressive effect." (PMID 39273396, 2024). "HIF‐1α is a pivotal regulator that can activate the transcription of genes associated with tumor angiogenesis and cell survival, such as VEGF and its receptor VEGFR." (PMID 39184861, 2024). "High levels of ROS can promote can promote the polarization and production of tumor-associated macrophages and the accumulation of hypoxia-inducible factor-1α (HIF-1α)." (PMID 38880903, 2024). "Its effect was associated with a decrease in the protein level of HIF-1α (1/4 control groups) and a strong increase in oxygen level in tumor tissue." (PMID 39138299, 2024). "In summary, loss of HIF1α in T cells impairs their tumor killing capacity and renders tumor-bearing mice resistant to ICBs, revealing a major T cell-intrinsic mechanism of therapeutic resistance to ICBs, which can be overcome by acetate supplementation." (PMID 39477954, 2024). "Tumor cell expansion, coupled with HIF-1α overexpression, promotes EMT, triggering loss of cell-to-cell adhesion through upregulation of EMT transcription factors, including Snail, Slug, Twist, and ZEB1." (PMID 38339408, 2024). "Studies have linked elevated HIF-1α expression to larger tumor sizes, higher tumor grades, increased proliferation markers (like Ki-67), and unfavorable molecular subtypes, such as HER2-positive and triple-negative breast cancers." (PMID 38396737, 2024). "While the accumulation of lactic acid within TME has been suggested as the main mechanism underlying impaired T cell anti-tumor response driven by hypoxia, the impact of HIF-1α on T cell is as yet controversial." (PMID 38175205, 2024). "HIF1α mediates the cellular response to hypoxia, which is a hallmark of the tumor microenvironment in many solid tumors." (PMID 39697237, 2024).